SAFB2 (scaffold attachment factor B2)
Description:
Binds to scaffold/matrix attachment region (S/MAR) DNA. Can function as an estrogen receptor corepressor and can also inhibit cell proliferation.
Synonyms: KIAA0138
Tractability: PROTAC: UniProt records ubiquitination sites on it; ubiquitination databases record sites on it; its protein half-life has been measured.
Gene: Protein-coding gene on chromosome 19 (5,586,981 to 5,624,046, reverse strand). Ensembl gene ENSG00000130254.
Subcellular location: Cytoplasm; Nucleus
Subcellular location (Human Protein Atlas): Nucleoplasm; Nuclear bodies; Vesicles
Gene Ontology:
Molecular function: identical protein binding; protein binding; RNA binding; nucleic acid binding
Biological process: regulation of androgen receptor signaling pathway
Cellular component: extracellular exosome; nuclear body; nucleoplasm; nucleus; cytoplasm
Genetic constraint (gnomAD): Loss-of-function variants: 29 observed, 81.27 expected, observed/expected ratio (o/e) 0.36, 90% interval 0.26 to 0.49. The upper end of that interval is the gene's LOEUF score, 0.49, which puts it in group 2 of 6, group 1 being the genes least tolerant of losing a copy. Missense variants: 1,044 observed, 1,032.5 expected, observed/expected ratio (o/e) 1.01, 90% interval 0.96 to 1.06. Synonymous variants: 443 observed, 390.05 expected, observed/expected ratio (o/e) 1.14, 90% interval 1.05 to 1.23.
Homologues: Orthologues: macaque SAFB2 (99% identical), chimpanzee SAFB2 (94% identical), dog SAFB2 (89% identical), pig SAFB2 (86% identical), guinea pig SAFB2 (81% identical), mouse Safb2 (73% identical), rat Safb2 (73% identical), Drosophila melanogaster Saf-B (28% identical), Caenorhabditis elegans phm-2 (23% identical). Paralogues in human: SAFB (71% identical), SLTM (37% identical).
Diseases named in the same sentence as SAFB2 in open-access papers:
SAFB2 is named in the same sentence as 9 diseases in open-access papers, as found by Europe PMC text mining. Sharing a sentence is not in itself a finding about the gene and the disease. The quoted sentences say what the papers report.
breast carcinoma (5 papers, 2008 to 2025). "The same study also reported that in breast cancer patients, low SAFB2 levels are associated with worse outcome in breast cancer patients." (PMID 31877708, 2019). "SAFB2 have also been implicated in breast tumorigenesis and have been reported to be frequently lost in breast cancer due to mutation, while its overexpression results in breast cancer growth inhibition." (PMID 31877708, 2019). "Somatic mutations of SAFB1 and SAFB2 have previously been observed in tumour DNA, but to our knowledge this is the first study of germline DNA from patients with hereditary breast cancer." (PMID 19077293, 2008). "In this study we investigated the possible involvement of SAFB1/SAFB2 on familiar breast cancer by inherited mutations in either of the two genes." (PMID 19077293, 2008). "Given that SAFB2 has been reported to inhibit breast cancer progression through the Wnt/β-Catenin pathway, we further explored its role in PDAC." (PMID 40308776, 2025). "Previous study suggested the scaffold attachment factor B2 (SAFB2) protein as a tumor suppressor involved in breast cancer development." (PMID 31877708, 2019). "The growing interest in SAFB1 and SAFB2 proteins in relation to cancer is generated from their well described ability to bind to and modulate ER-α, a central player in breast cancer development." (PMID 26273616, 2015). "The expression of Safb2 protein, which functions as estrogen receptor co-repressor and growth inhibitor, was lost in approximately 20% of breast cancers." (PMID 23555558, 2013). "The scaffold attachment factor B1 and B2 genes, SAFB1/SAFB2 (both located on chromosome 19p13.3) have recently been suggested as tumour suppressor genes involved in breast cancer development." (PMID 19077293, 2008). "Additionally, beyond repressing AR and ERα activity, SAFB2 has been shown to suppress breast cancer progression by inhibiting the Wnt/β-catenin pathway via NFAT5." (PMID 40308776, 2025). "Further work will now be undertaken to define whether SAFB1 and SAFB2 function synergistically or compensatory as RNA-binding proteins in breast cancer cells." (PMID 26273616, 2015). "The observed loss of SAFB1 in both breast cancer cell lines does not have an effect on ITGB4 mRNA expression whereas loss of SAFB2 and both SAFB proteins significantly increased ITGB4 expression." (PMID 26273616, 2015). "SAFB1 and SAFB2 are not likely to be causative of the hereditary breast cancer syndrome in west Swedish breast cancer families." (PMID 19077293, 2008). "Using RNAi, we also show, for the first time, that single depletion of either SAFB1 or SAFB2 leads to an increase in expression of the other SAFB protein in both MCF-7 and MDA-MD231 breast cancer cells." (PMID 26273616, 2015).
breast tumours (1 paper, 2008). "Somatic mutations in SAFB1/SAFB2 have been detected in breast tumours, but to our knowledge no studies on germline mutations have been reported." (PMID 19077293, 2008).
epilepsy (1 paper, 2025). A brain disorder characterized by episodes of abnormally increased neuronal discharge resulting in transient episodes of sensory or motor neurological dysfunction, or psychic dysfunction. "Notably, a clinical study reported that SAFB1 and SAFB2 might be responsible for epilepsy and mental retardation in a patient." (PMID 41497586, 2025).
ovarian carcinoma (1 paper, 2021). A malignant neoplasm originating from the surface ovarian epithelium. "Our results showed that SAFB2 was significantly underexpressed in ovarian cancer." (PMID 33550985, 2021).
renal cell carcinoma (1 paper, 2021). "Previous studies revealed that SAFB2 could be a biomarker in breast and renal cell cancers." (PMID 34194501, 2021).
cancer (5 papers, 2013 to 2025). A tumor composed of atypical neoplastic, often pleomorphic cells that invade other tissues. "SAFB2 (scaffold attachment factor B2) is a multifunctional protein involved in a variety of cellular processes, known for its role in transcriptional inhibition, and has potential for cancer suppression." (PMID 33550985, 2021). "There is numerous evidence that SAFB1/SAFB2 have a contribution in cancer progression." (PMID 26482227, 2015). "This SAFB2–/– mouse model provides a unique system to study SAFB2 function in the normal male reproductive system, as well as in pathophysiological conditions such as cancer." (PMID 26092125, 2015). "SAFB1/SAFB2 may have more complex implications in cellular functions, such as RNA processing and metabolism, that could potentially affect various signalling pathways in cancer." (PMID 26482227, 2015).
tumor (5 papers, 2008 to 2025). "While our findings suggest that SAFB2 has tumor-suppressive potential in PDAC, its precise role and underlying regulatory mechanisms, particularly in relation to the inhibition of Wnt/β-Catenin signaling and suppression of tumor progression, remain to be fully elucidated." (PMID 40308776, 2025). "Of particular note, CNV analysis of the three key prognostic genes in the Sscore model revealed that the deletion frequency of SAFB2 was substantially higher in High-Sscore patients, suggesting that loss of SAFB2 may contribute to tumor progression." (PMID 40308776, 2025). "In summary, our study presents a novel SUMOylation substrate encoding gene model for predicting PDAC prognosis and unveils SAFB2 as a promising tumor suppressor." (PMID 40308776, 2025). "Overall, our study establishes a novel three-gene SUMOylation substrate prognostic model and highlights the important tumor-suppressive function of SAFB2 in PDAC." (PMID 40308776, 2025). "In conclusion, our findings demonstrate a strong association between the Sscore and genome variation in PDAC patients, highlighting SAFB2 as a critical target for further investigation in tumor progression." (PMID 40308776, 2025). "CNV analysis further revealed a higher frequency of SAFB2 deletions in high Sscore patients, implicating SAFB2 as a potential tumor suppressor in PDAC." (PMID 40308776, 2025). "In hormone-dependent cancers, including breast and prostate cancers, SAFB2 expression is downregulated and delays tumor progression by inhibiting the transcriptional activities of androgen receptors (AR) and estrogen receptors α (ERα)." (PMID 40308776, 2025). "In RCC, exosomal circ-SAFB2 reshapes the tumor environment, mediates M2 macrophage polarization, and promotes tumor progression." (PMID 37525158, 2023). "There is also the risk of another tumour suppressor gene located in the close vicinity of SAFB1 and SAFB2 that would be the true basis for the observed linkage to the region." (PMID 19077293, 2008). "Combining Wnt pathway inhibitors (e.g., PRI-724, LGK974) with SAFB2 overexpression strategies may provide synergistic tumor suppression." (PMID 40308776, 2025). "The observed downregulation of SAFB2 highlights its potential tumor-suppressive function, with in vitro experiments demonstrating its inhibitory effects on PDAC cell proliferation, migration and invasion, possibly through suppression of the Wnt/β-Catenin pathway." (PMID 40308776, 2025). "Moreover, the downregulation of SAFB2 in PDAC cells suggests that it may exert tumor-suppressive effects by inhibiting the Wnt/β-Catenin pathway, pointing to potential novel therapeutic avenues for PDAC." (PMID 40308776, 2025). "SUMOylation enhances the transcriptional repression ability of SAFB2, particularly immune-related genes like MHC-I, enabling tumor cells to evade immune detection by reducing antigen presentation, thus promoting immune escape." (PMID 40308776, 2025). "Of note, we identified newly emerged 8 non-synonymous somatic mutations of the genes (ACAP2, CARD10, KIAA0556, PAAQR7, PPP1R39, SAFB2, STARD9, and ZFYVE9) in the imatinib-resistant tumor tissue." (PMID 23922791, 2013). "In conclusion, this study did not reveal any pathogenic germline mutations and no apparent genomic deletions in SAFB1 or SAFB2, and the hypothesis that the two genes would function as tumour suppressor genes could not be verified in this patient based material." (PMID 19077293, 2008). "While the expression and function of SAFB2 in PDAC remain understudied, its established tumor-suppressive role suggests that it may be critical in PDAC progression." (PMID 40308776, 2025). "Further in vitro studies revealed that overexpression of SAFB2 significantly inhibited the proliferation, invasion, and migration of PDAC cells by suppressing the Wnt/β-Catenin signaling pathway, indicating its potential role as a tumor suppressor in PDAC." (PMID 40308776, 2025).
SAFB2 also shares sentences with these, for which no sentence is quoted: Obesity (1 paper); pancreatic ductal adenocarcinoma (1).